EGFR (epidermal growth factor receptor)
Diseases named in the same sentence as EGFR in open-access papers (continued):
Sharing a sentence is not in itself a finding about the gene and the disease.
lung cancer (continued). "In 89 patients with lung cancer and 27 individuals without, we measured serum hTERT mRNA and epidermal growth factor receptor (EGFR) mRNA levels, using a quantitative one-step real-time RT-PCR assay." (PMID 21892326, 2008). "In lung cancers, increased EGFR gene copy number was also reported not to be consistently accompanied by positivity for EGFR protein, as assessed by immunohistochemistry." (PMID 18950515, 2008). "As T790M-EGFR may play a role in both intrinsic and acquired EGFR-TKI resistance in lung cancer, it would be useful to test concurrent combinatorial MET–EGFR inhibitors in clinical trials on lung cancer patients refractory to erlotinib/gefitinib." (PMID 19238632, 2008). "Its activated form, phosphorylated EGFR (pEGFR), is correlated with poor prognosis in lung cancer, but it has not yet been fully investigated in breast cancer." (PMID 18522728, 2008). "Furthermore, oncogenic and immune checkpoint proteins, such as EGFR, ALK, KRAS G12C, and PD-L1, which are well-established in lung cancer, could be monitored in fibrotic patients to detect early malignancy or to guide preventive therapies." (PMID 41375062, 2025). "For example, CAFs can over‐secret ANXA2, which triggers EMT in lung cancer cells; this pro‐EMT phenotype is dependent on the secretion of hepatocyte growth factor (HGF) and insulin‐like growth factor 1 (IGF1) by CAFs, thus facilitating the cancer cells' evasion of EGFR targeting." (PMID 40162549, 2025). "The progress in precision medicine, with Epidermal Growth Factor Receptor (EGFR) inhibitors, Anaplastic Lymphoma Kinase (ALK) inhibitors, and immune checkpoint inhibitors, has significantly improved survival and quality of life for patients with advanced lung cancer." (PMID 40452440, 2025). "Related studies have also shown that combined cytotoxic chemotherapy and EGFR-TKI treatment can help improve the remission rate and PFS rate of SCLC transformation, so in addition to the treatment of SCLC, we should also pay attention to the treatment of the primary lung cancer type." (PMID 40134592, 2025). "For lung cancer cells resistant to epidermal growth factor receptor (EGFR) tyrosine kinase inhibitors (TKI), the use of DNMTi or HDACi can alter the epigenetic modifications of drug resistance-related genes, partially restoring the sensitivity of lung cancer cells to TKI." (PMID 41394878, 2025). "Results showed a significant decrease in EGFR, CBP, and SMARCB1 at mRNA and protein levels, and a significant increase in mRNA of EZH2, but no significant change in protein levels for EZH2, suggesting that both MEOX2/GLI-1 modulate these tumor and epigenetic markers in lung cancer A549 cells." (PMID 39971779, 2025). "EAE and Acetone extract reduced cell viability in a dose-dependent manner in H1975 (EGFR_T790M+), A431 (wtEGFR), H1299 (nRAS-driven Lung Cancer), and A549 (kRAS-driven Lung Cancer) cell lines compared to the non-cancerous EGFR-negative Jurkat cell line (T-lymphocyte)." (PMID 40365309, 2025). "However, in studies investigating the effect of bufalin on lung cancer cells immediately afterwards, it was shown that it was effective by inhibiting the phosphorylation of the EGFR protein without affecting EGFR protein levels." (PMID 40172364, 2025). "Furthermore, our results suggest that BRD9 may contribute to the activation of both lung cancer oncogenes GLI-1 and EGFR." (PMID 39971779, 2025).
lung cancer (continued). "Notably, EAE demonstrated selective inhibition of EGFR-positive lung cancer cells, and no significant inhibition, even at higher extract concentrations, of the EGFR-negative Jurkat cells was observed." (PMID 40365309, 2025). "Resistance to tyrosine kinase inhibitors of EGFR in NSCLC is driven by constitutive activation of S6K1, with p-S6K1 levels higher in the gefitinib-resistant lung cancer cells and PDX tumors compared to the gefitinib-sensitive lung cancer and parental PDX tumors, respectively." (PMID 39781466, 2025). "SCAN-ACT identified 174 monospecific CAR-T targets in GBM, including several established GBM CAR-T targets such as CD276, EGFR, IL13RA2, ROBO1, as well as targets studied in different diseases like GPC2 in neuroblastoma, IL11RA in osteosarcoma, or DLL3 in lung cancer." (PMID 40814001, 2025). "Epidermal growth factor receptor (EGFR)–mutant nonsquamous NSCLC was the first type of lung cancer identified with an oncogenic driver that could be directly targeted by drug treatment." (PMID 40029742, 2025). "Outcomes from routine treatment with erlotinib and gefitinib in New Zealand patients with advanced EGFR-mutant nonsquamous non–small cell lung cancer are comparable with those reported in randomized trials and other health care system–wide retrospective cohort studies." (PMID 40029742, 2025). "Atezolizumab, bevacizumab, carboplatin, and paclitaxel (ABCP) therapy is beneficial for epidermal growth factor receptor‐tyrosine kinase inhibitor (EGFR‐TKI)‐resistant non‐small cell lung cancer (NSCLC); however, the resistance mechanisms are not fully understood." (PMID 40843133, 2025). "We also explored the total and phosphorylated levels of EGFR and HER3, because persistent or constitutively active signaling through RTKs occurs in many solid tumor types including subtypes of breast cancer (HER2) and lung cancer (EGFR), especially when the gene is amplified." (PMID 40906535, 2025). "However, it was equally effective against the EGFR-negative non-lung cancer Jurkat cell line, suggesting its non-specific cytotoxicity against all cell types." (PMID 40365309, 2025). "Exosomal proteomes have identified several exosomal proteins, including CD317, EGFR, leucine-rich a2-glycoprotein (LRG1), alpha-2-HS-glycoprotein (AHSG), and extracellular matrix protein 1 (ECM1), that hold the potential to serve as indicators for lung cancer early detection." (PMID 40559625, 2025). "As a highly selective inhibitor of AURKB, AZD1152 can overcome resistance to EGFR inhibitors in lung cancer via enhancing apoptosis, modulate paclitaxel response in non–small cell lung cancer, and enhance chemotherapeutic efficacy in pancreatic and colon cancers." (PMID 39927464, 2025). "However, the mechanisms by which mutant EGFR in lung cancer affect the biogenesis and cargo composition of EVs have not been thoroughly investigated." (PMID 40210802, 2025). "Multiple papers have demonstrated that EGFR is required in pancreatic and lung cancer models driven by oncogenic K-Ras, and that oncogenic Ras activity (GTP-binding) and ERK phosphorylation are substantially reduced by ablation or inhibition of the EGFR, paralleled by reduced tumorigenesis." (PMID 41132131, 2025). "The LUAD dataset lacked mutational profiling such as EGFR, ALK, or KRAS status, which are key determinants of prognosis in lung cancer and could influence spatial associations with survival." (PMID 40723219, 2025). "Hence, the primary aim of our study is to comprehensively evaluate the clinical manifestations, therapeutic outcomes and molecular profiles of advanced EGFR-positive nonsquamous lung cancer patients within our tertiary care setting in Pakistan." (PMID 41333366, 2025). "There is reason to believe that EGFR plays a prominent role in inducing LUAD through this pathway, since it exhibits a high frequency of mutations and has been identified as a prognostic factor for lung cancer in never smokers (LCINS)." (PMID 40768543, 2025).
lung cancer (continued). "Finally, the current bsAbs are mainly targeted at some mature targets (e.g., EGFR, PD1, etc.), and breakthroughs are urgently needed in the mining of new lung cancer-specific targets (e.g., c-MET, HER3) and TME regulation strategies (e.g., combining with anti-angiogenic drugs)." (PMID 40510353, 2025). "MMAE-conjugated VBC101-F11 displayed superior TGI over ABBV-399 in lung cancer cell line xenografts (3 mg/kg), and conjugation to a novel, undisclosed DNA replication inhibitor resulted in similar efficacy to AZD9592 in EGFR-low/c-MET-high and EGFR-/c-MET-moderate models." (PMID 39065587, 2024). "Significantly, DUSP22 failed to inhibit colony formation in EGFRlow H520 and TC-1 cells, suggesting that DUSP22 predominantly acts on EGFR and hinders EGFR signaling to impede lung cancer cell proliferation via dephosphorylation, regardless of their EGFR mutation status." (PMID 38877005, 2024). "However, HPV-positive lung cancers seem to have a better prognosis compared to negative forms and an improved response to target therapies (EGFR), immune checkpoint inhibitors, and platinum-based chemotherapy." (PMID 38255725, 2024). "The vascular endothelial growth factor (VEGF) pathway plays a critical role in driving oncoangiogenesis in lung cancer and dual inhibition of VEGF signaling and EGFR signaling pathways offers the prospect of improving the effectiveness of EFGR-targeted therapy and overcoming EGFR-TKI resistance." (PMID 39134529, 2024). "In conclusion, while the efficacy of EGFR-TKIs in EGFR-mutant LSCC may not be as pronounced as in other types of lung cancers, they still lead to improved outcomes compared with chemotherapy." (PMID 39166093, 2024). "However, EGFR-mutated and ALK-rearranged lung cancers represent no more than 15% of patients with lung cancer." (PMID 39123495, 2024). "Remarkably, we have seen a significant (ES = −0.59, P < 0.01) overlap of the gene set down-regulated in EGFR inhibitor-treated NSCLCs and the genes altered by C22orf46 knockout when using the “chemical and genetic perturbations” (CPG, customized for lung cancer) collection." (PMID 38228372, 2024). "Here, we integrate studies in patient-derived and immunocompetent lung cancer models and clinical specimens obtained from patients on targeted therapy to uncover a focal adhesion kinase (FAK)-YAP signaling axis that promotes residual disease during oncogenic EGFR-, ALK-, and KRAS-targeted therapies." (PMID 38702301, 2024). "Moreover, a global decrease in H3K27me3 or accumulation of H3K9me3 has been observed in triple-negative breast cancer cells after chemotherapy and in lung cancer cells after treatment with a tyrosine kinase inhibitor of the EGFR, respectively." (PMID 38669046, 2024). "Human never-smoker lung cancer is primarily non-small cell lung cancer (NSCLC), which accounts for 10–25% of cases and is characterized by a high incidence of gene mutations, such as those affecting EGFR." (PMID 39902337, 2024). "We hypothesized that L3MBTL1 primarily compacts chromatin by combining with H4K20Me2 in EGFR-TKI-acquired drug-resistant lung cancer cells, because 53BP1 did not bind to H4K20Me2, reducing DNA damage after Osimertinib treatment of Osimertinib-resistant cells." (PMID 39231972, 2024). "Therefore, we aimed to compare the clinical characteristics of ICI-treated and non-treated patients with EGFR-mutant lung cancers and to investigate the characteristics of those who benefited from immunotherapy in a prospective registry cohort of NSCLC." (PMID 38347279, 2024).
lung cancer (continued). "The results of these two studies suggest that ctDNA-based EGFR genotyping could help provide viable diagnoses in lung cancer patients for whom tissue biopsy is not possible." (PMID 36835972, 2023). "In addition, G9a in lung cancer increases H3K9me2 levels at the PTEN promoter to suppress its transcription, thereby activating the AKT signaling pathway and contributing to the development of resistance against EGFR tyrosine kinase inhibitors (EGFR-TKIs)." (PMID 37394580, 2023). "HCPT combined with CRI possessed the synergistic inhibition of proliferation and inducing cell apoptosis by inactivating of EGFR related downstream signalling pathways and the conjugate CH-1 significantly suppressed the lung cancer cell growth with no observed toxicity." (PMID 36305251, 2023). "Compared with the lung cancer HCC827 cells in the control group, the icotinib treatment group inhibited the activation of the downstream MAPK/ERK signaling pathway by inhibiting the autophosphorylation of EGFR, and it also inhibited the proliferation of HCC827 cells." (PMID 36674593, 2023). "In addition, PA induced cell cycle arrest and apoptosis in vitro and in vivo by blocking phosphorylation of the epidermal growth factor receptor (EGFR) pathway and activation of the c‐Jun N‐terminal kinase (JNK) signalling pathway in A549 human non‐small cell lung cancer cells." (PMID 37038620, 2023). "The undeniable role of this transmembrane protein in the pathogenesis of lung cancer underscores the significance of EGFR not only for the current review but for lung cancer research in general, even though the range of EGFR-related health issues is not very broad." (PMID 37754880, 2023). "Hence, the importance of AhR-Cav1 crosstalk likely extends beyond regulation of EGFR and warrants further studies into the role of non-genomic AhR signaling in ordered membrane microdomains for development of lung cancer." (PMID 37696458, 2023). "Additionally, NEU3 is a promising biomarker for evaluating EGFR-targeted therapies in patients with NSCLC, and the expression level of GTs in lung cancer tumors may act as a biomarker for the diagnosis, prognosis, and treatment assessment." (PMID 37256139, 2023). "Furthermore, oncofetal CS expression was recently studied in lung cancer, and elevated levels were found to predict poor disease-free and overall survival in early-stage NSCLC independent of the presence of KRAS and EGFR mutations." (PMID 37108213, 2023). "EGFR amplification was not restricted to KDD in lung cancer." (PMID 36325957, 2023). "Having demonstrated the oncogenic capacity of LAMC2 in lung cancer as well as its ability to enhance EGFR expression and signaling through facilitating protein transport and stabilization, we went on to assess the importance of LAMC2 expression on EGFR TKI sensitivity." (PMID 37542131, 2023). "Variant-specific PCR was performed for 744 tumors with a normal 5′/3′-end expression ratio: there were no rearrangements in 172 EGFR/ALK/ROS1/RET/MET-negative lung cancers and 125 pediatric tumors, while NTRK3 fusions were detected in 2/447 (0.5%) non-lung adult malignancies." (PMID 37762506, 2023). "Thus, we conducted a correlation study between FGF11 and EGFR (19DEL, L858R), EGFR (Exon 20ins), KRAS (G12C), ALK, ROS1, BRAF, NTRK1/2/3, MET, and RET, which are all recommended by the NCCN guidelines for the diagnosis of nonsmall cell lung cancer." (PMID 37250453, 2023). "Studies of advanced lung cancer patients in the United States suggest that there may be SES‐based inequalities in survival, in the use of breakthrough palliative treatments, and geography‐based inequalities in the delay to initiate EGFR‐TKI treatment." (PMID 37017510, 2023).
lung cancer (continued). "The hypothesized positive association between EGFR alteration and VTE was not consistent with the previously reported lung cancer literature, as EGFR non-amplified elderly glioblastoma patients were at an increased risk of VTE." (PMID 37232831, 2023). "When considering that TMB is obviously associated with smoking status and that EGFR‐mutant lung cancer is mostly found in nonsmokers, it is probable that low TMB in EGFR‐mutant lung cancer could affect the efficacy of immunotherapy." (PMID 37699785, 2023). "However, we found that in DMS114 cells and other EGFR-positive lung cancer cells such as HCC15, EGF administration did not affect the cytotoxicity of taltobulin." (PMID 37509496, 2023). "However, how long for the application of bisphosphonates application is still not clear for patients with BM of lung cancer, especially in patients with BM from lung adenocarcinoma of EGFR‐mutant." (PMID 35614541, 2023). "In lung cancer, AKR1B1 is a STAT3 activator that promotes glutathione de novo synthesis, eliminates ROS, protects cell from death, and reduces EGFR TKI drug sensitivity by upregulating the cystine transporter SLC7A11, it would be a therapeutic target for dealing with EGFR TKI resistance." (PMID 36512456, 2023). "However, the role of EGFR-TKIs in advanced-stage lung cancer is uncertain regardless of therapeutic methods." (PMID 37833769, 2023). "Immunotherapy in patients with EGFR‐mutant lung cancer is not so effective." (PMID 37699785, 2023). "In lung cancer cell lines and PDX models, aldo-keto reductase family 1 member B1 (AKR1B1) promoted glutathione de novo synthesis by activating signal transducer and activator of transcription 3 (STAT3), leading to ROS scavenging and ultimately to EGFR-TKI drug resistance." (PMID 36911198, 2023). "Data from whole‐exome sequencing, targeted deep sequencing, and single‐nucleotide polymorphism arrays by Hong and co‐workers revealed that pulmonary LEC resembles NPC more closely relative to other lung cancers, which may explain the similar responses of lung LEC and NPC to EGFR‐TKI." (PMID 36464832, 2023). "Furthermore, ID2-inhibition of endogenous EGFR protein level can be reversed by F-78(WT) but not F-78(NLS Mut) in H1975 human lung cancer cells and HEK293AD cells." (PMID 37487081, 2023). "Increasing expressions of the EGFR and MOR in lung cancer could promote growth of tumor cells, trigger angiogenesis mediated by the vascular endothelial growth factor (VEGF), increase vascular permeability, accelerate tumor progression, and increase the risk of micrometastasis." (PMID 35966857, 2022). "Additionally, suppressing the catalytic activity of Src by DNAJB4, which functions as an endogenous Src inhibitor, can downregulate EGFR, FAK, and STAT3 downstream signaling pathways, leading to inhibition of epithelial–mesenchymal transition (EMT) and metastasis of lung cancer cells." (PMID 36499297, 2022). "Despite the apparent effects of HER3 mutations on lung cancer biology, no large-scale clinical trials have been conducted to validate a specific treatment strategy for ERBB3-mutant lung tumors, in contrast to activating EGFR mutations." (PMID 36476337, 2022). "Unlike other oncogenic addicted tumors, namely EGFR driven lung cancer (NSCLC), where the appearance of secondary mutation in the target gene (EGFR) is a common mechanism of resistance to EGFR inhibitors, no BRAF secondary mutation has been so far reported in BRAFi‐resistant melanomas." (PMID 36305167, 2022). "By using a KrasG12D-induced spontaneous lung cancer mouse model and Zdhhc20 knockout mice, researchers demonstrated that the ablation of ZDHHC20 or induction of EGFRC1025A mutant inhibited tumorigenesis, which seems contradictory to the increased EGFR activation." (PMID 36577755, 2022). "Since we understand that TKI can not eradicate all EGFR positive cancer cells in stage IV lung cancer, a prolonged EGFR TKIs exposure may result in significant benefits." (PMID 35360423, 2022).